PAK1 (p21 (RAC1) activated kinase 1)
Diseases named in the same sentence as PAK1 in open-access papers (continued):
Sharing a sentence is not in itself a finding about the gene and the disease.
tumor (continued). "COL4A1 manages the inhibition of cell death; the activation of focal adhesion kinase; the cell cycle; tumor angiogenesis; the PI3K/MAPK, PI3K/AKT, and PRL/PAK1 signaling pathways, and the discoidin domain receptor (DDR) axes." (PMID 38004422, 2023). "Initial studies unveiled an integral role of PAK1 in the regulation of PCa EMT in vitro and the growth of tumor xenografts in vivo." (PMID 37190165, 2023). "Western blotting and qPCR results indicated that HOXD9, PABPC1, and PAK1 were usually upregulated, whereas PAXIP1-AS1 was frequently downregulated in the 15 tumour samples examined compared to that in the paired paracancerous tissues from the same patient." (PMID 37225681, 2023). "In NMFH1 xenografts, PF3758309 treatment dose-dependently decreased the expression levels of whole-cell PAK1 and nuclear p-PAK1 and correspondingly led to lower Ki-67 index and MVD, hence achieving significant tumor growth inhibition." (PMID 37564209, 2023). "Copy numbers were estimated by counting the number of fluorescent signals for PAK1 and CEP11 in 20 tumour cell nuclei." (PMID 37368917, 2023). "Our study in a PCa tumor xenograft model demonstrated impaired tumor angiogenesis with PAK1 or PAK6 gene knockdown, with PAK1 suppression exhibiting a superior anti-angiogenic effect than PAK6 suppression." (PMID 37190165, 2023). "Through β-catenin, Rac1/PAK1 can facilitate EMT, which is an essential condition for the invasion and metastasis of tumor cells." (PMID 37049739, 2023). "The combined effects of sorafenib and amiloride on tumor growth, the area of necrosis, and the levels of phosphorylated AKT, PAK1, and 4-HNE after blocking macropinocytosis were further verified in orthotopic RIL-175 tumors transplanted into C57BL/6 mice." (PMID 35287706, 2022). "In HCC, upregulated CDC42 has been also found in the tumor cell lines, and CDC42 can also promote the expression of PAK1 to advance the malignant behaviors of the tumor cells." (PMID 35340237, 2022). "In the xenograft tumor tissue overexpressing circBRWD3, RAC1, PAK1, and p- PAK1 were dramatically upregulated, while in the tissue with circBRWD3 knockdown, they were significantly downregulated." (PMID 36443711, 2022). "To address the first question, we correlated the microarray-based mRNA expression of the 5 CSA targets (EIF2AK3, MAPK12/p38γ, PAK1, RPS6KA3, and WNK3) in a panel of 60 tumor lines of the NCI, USA, with 83 standard anticancer agents." (PMID 35163434, 2022). "We collected the xenograft tumor tissues from the mice and quantified the levels of the key molecular components of the RAC/PAK1 signaling." (PMID 36443711, 2022). "Consistent with the role of RAC1, PAK1, and CDC42 in regulating inducible macropinocytosis, analysis of the TCGA dataset revealed higher expression of RAC1, PAK1, and CDC42 in HCC tissues than in non-tumor lesions." (PMID 35287706, 2022). "Regarding Pak1, we found that the expression level of this kinase is elevated in Luminal A, Luminal B and TNBC tumor samples." (PMID 35111748, 2021). "Overall, we found a strong correlation between Pak1 and CaMKII expression in Luminal A, Luminal B and TNBC tumor samples (r2 = 0.631, p < 0.0001)." (PMID 35111748, 2021). "Particularly, PAK1 and PAK4 are often upregulated in human tumors, and the tumor cells with upregulated PAK1 and PAK4 tend to become dependent on PAK signaling." (PMID 34471161, 2021). "On the one hand, PAK1 takes part in HER2, EGFR, MAPK, PI3K/AKT, and Wnt/β-catenin pathways and properly coordinates these signals to ensure tumor cell proliferation under hypoxic conditions." (PMID 32863957, 2020). "We evaluated PAK1 mRNA and protein expression in NSCLC cells and resected tumor specimens, as well as in healthy human bronchial epithelial cells and adjacent healthy lung tissues, respectively, for effective comparison." (PMID 33261184, 2020).
tumor (continued). "miR-7 also directly targets insulin-like growth factor 1 receptor (IGF1R), FAK, and PAK1, which can inhibit the proliferation, migration, invasion, and epithelial-mesenchymal transition (EMT) of tumor cells." (PMID 32090067, 2020). "In this study, we found that p21-activated kinase (PAK1) inhibitor (Group I, PAK inhibitor, IPA-3) and inactivator (ivermectin) treatments inhibit cell proliferation and that tumor growth of PAK1-knockout cells in a mouse model is significantly reduced." (PMID 31658701, 2019). "Both FRAX1036 and the combination treatment effectively and significantly reduced phospho-PAK1/2/3 in BT474 and T47D tumor cell lines." (PMID 31254157, 2019). "Enhanced anti-tumor activity of this combination is based on multiple mechanisms, including enhanced inhibition of phosphorylation of AURKA, PAK1, and ERα, as well as decreased expression of cell cycle proteins and C-MYC." (PMID 31254157, 2019). "Many potential targets of miR-7 were reported to participate in some important signalling of tumor progression, such as targets EGFR, IRS-1, PAK-1, RAF-1, SATB1, and so on." (PMID 28239300, 2017). "Knocking down of PAK1 inhibited DU145 cell growth, invasion and migration in vitro, and inhibited tumor growth in vivo." (PMID 28186966, 2017). "This conclusion is strongly supported by the observation that the numbers of tumours in the small intestine of PAK1 heterozygous (het) APC∆14/+ and PAK1 knockout (KO) APC∆14/+ mice were reduced by over 50% compared to PAK1 wild type (WT) APC∆14/+ mice." (PMID 28629331, 2017). "P21-activated kinase 1 (PAK1) is a member of a family of serine/threonine kinases and regulates cell growth and contributes to tumor invasion and metastasis." (PMID 28186966, 2017). "Tumours isolated from the small intestine and colon/rectum of APC∆14/+ mice have greater protein levels of PAK1, β-catenin and hypoxia-inducible factor 1α (HIF-1α) compared to normal intestinal tissue." (PMID 28629331, 2017). "Thus, PAK1 may be a potential tumor marker and therapeutic target of PCa." (PMID 28186966, 2017). "These tumours are characterized by co-amplification of CCND1 and PAK1 at 11q13–14, and have previously been shown to be resistant to neo-adjuvant cytotoxic chemotherapy." (PMID 27161491, 2016). "Nonetheless the role of PAK1/PAK2 as potential target for KRAS MT NSCLC, especially for tumor showing dependency from KRAS, merits further evaluation as potential therapeutic target." (PMID 26468985, 2015). "It appears that combination of prenylation inhibitors and PAK1 inhibitor adequately disrupt the signaling network downstream of KRAS and provide a prominent anti-tumor effect." (PMID 25956913, 2015). "Mechanistic dissection revealed that miR-203 mediated cell proliferation, adhesion and invasion in vitro, and tumor growth in vivo, as evidenced by reduced RAC1, p-PAK1, and p-MEK1 expression." (PMID 25636908, 2015). "To assess the role of Pak1 and Pak2 in vivo, we stereotactically injected shRNA-transduced KT21 cells to the skull base of SCID mice and monitored tumor growth by bioluminescence imaging (BLI)." (PMID 25596744, 2015). "By repressing Pak1 expression, Rb could prevent the Rac1 hyperactivity that has been previously related to the disruption of adhesive structures in epithelial cells, a process that can exacerbate metastasis by promoting detachment of tumor cells from the primary site." (PMID 26555075, 2015). "The suppression of Nischarin and LKB1 in these cells resulted in increased phosphorylation of PAK1 and LIMK1, and upregulation of Cyclin D1 and CDK4 expression, resulting in enhanced cell migration and tumor growth." (PMID 25695373, 2015). "IPA-3 showed a significantly reduction in tumor growth from the MHCC97L cells and the effect of IPA-3 on PAK1 activity was demonstrated by the reduction of the phosphorylation levels of PAK1 and JNK." (PMID 23894351, 2013).
tumor (continued). "Immunohistochemical analysis showed that Klotho expression was positively correlated with PAK1 staining (n = 52, r = 0.5427, P<0.0001) in HCC tumor tissues." (PMID 23516476, 2013). "PAK1 and PAK2 have been shown to differentially modulate adhesion, RhoA activity and MLC phosphorylation during mast cell degranulation and tumor cell migration." (PMID 24019894, 2013). "We found that miR-7 functions as a “tumor suppressor” by targeting proteins in three major oncogenic pathways - EGFR, Pak1, and Ack1." (PMID 21454924, 2011). "In the present study, LVI, Pak1 activity, Rac1, pT stage, and tumor grade were related to postoperative recurrence according to univariate analysis, with both LVI and Pak1 still being significant determinants according to multivariate analysis." (PMID 20426825, 2010). "In order to take into account possible inter-individual variations of Rac1 activity and Pak1 protein expression in UC-UUT, we performed a comparison among paired samples of tumor tissue, metastatic lymph node tissue, and non-tumor tissue from the same patient." (PMID 20426825, 2010). "Elevated expression levels of Pak1 and LC8 in tumor tissues and growth of MCF-7 cells overexpressing Pak1 and LC8 in soft agar assays suggest that the LC8-Pak1 interaction is critical for tumor progression." (PMID 19557173, 2009). "The limited number of tumor samples being analyzed for both CGH and IHC reduced the chances of obtaining a significant P value, but for PAK1/Pak1 a significant positive correlation was observed between protein and gene expression (P = 0.027)." (PMID 18823530, 2008). "Through its kinase activity, PAK1 activates the RAF/MEK/MAPK pathway to promote proliferation, and its phosphorylation of MEK1 is key for focal adhesion formation, thereby enhancing tumour cell migration." (PMID 40070022, 2025). "The double knockout of PAK1 and PAK4 did not inhibit tumour growth significantly, but stimulated vascular normalisation, indicating an outcome balanced between PAK1 and PAK4." (PMID 41228228, 2025). "These complementary mechanisms suggest that combined PAK1 and PAK4 inhibition could enhance therapeutic efficacy through both vascular and tumour-intrinsic mechanisms." (PMID 41228228, 2025). "The downregulation of these markers suggests that knockout of PAK1 and/or PAK4 may suppress VM formation, thereby contributing to vascular normalisation and altered tumour vascular architecture observed in our models." (PMID 41228228, 2025). "We have found that complete absence of PAK1 reduced tumor multiplicity without affecting tumor size after azoxymethane (AOM)/DSS treatment." (PMID 40783411, 2025). "The established roles of PAK1 and PAK4 in regulating intra-tumoral T-cell responses suggest that these kinases may also influence the tumour vasculature." (PMID 40943273, 2025). "Though there is substantial evidence on the role of Pak1 in promoting tumorigenesis by regulating the cellular proliferative pathways, its involvement in altering the tumor cell metabolism is not much explored." (PMID 40090587, 2025). "Our data from proteomic analysis revealed an increase in Ly6c1 expression in PAK4KO tumours whereas PAK1 deletion did not change the expression of Ly6C." (PMID 40943273, 2025). "The expression of CD31 and CD34 was not changed in the PAK1&4KO tumours, indicating that PAK4KO dominated the effect on angiogenesis and compromised PAK1KO-decreased angiogenesis." (PMID 41228228, 2025). "VEGFD and PAK1, in particular, display strong positive correlations with bacterial load, and integrated coculture analyses confirm that MAPK signaling, mediated by VEGFD and PAK1, is a key driver of bacteria-facilitated tumor progression and metastasis." (PMID 41355895, 2025). "PAK1&4KO didn’t regress tumour growth significantly, nor the angiogenesis, suggesting that PAK4KO dominated the vascular regulation and thus tumour growth." (PMID 41228228, 2025).
tumor (continued). "PAK1&4KO didn’t reduce angiogenesis nor tumour growth, but promoted vascular normalisation, indicating the outcomes after balancing of PAK1 and PAK4." (PMID 41228228, 2025). "Comparably, our RNA-seq and qRT-PCR results showed that pak1 was down-regulated in pax3a−/−;pax3b−/− double mutants, in particular in the slow progressing tumours, which makes pak1 a plausible driver of fusion negative RMS progression in our model." (PMID 36229514, 2022). "Whether in Oncomine or in UALCAN, ADRB2, ARRB1, BDNF, etc., had a lower expression in tumor group than normal tissues, whereas CBLC, GPI, and PAK1 had a higher expression in tumor group than normal tissues." (PMID 35833114, 2022). "In order to further examine the relationship between PAK1 and AKT and pAKT, based on the CCLE database, we obtained the mRNA expression of PAK1 and AKT1 in tumor cell lines, the protein levels of AKT and pAKT in tumor cell lines, and analyzed the PAKs mRNAs and their correlations." (PMID 36064705, 2022). "In addition, due to the lack of PAK7 data in the GSVA database, we grouped 28 tumor patients according to the methylation status of PAK1, PAK2, PAK3, PAK4, and PAK6, respectively, and then analyzed the survival difference of tumor patients." (PMID 36064705, 2022). "Overall, both Pak1 and CaMKII showed higher expression levels in tumor samples than in non-transformed adjacent tissue (p < 0.0001)." (PMID 35111748, 2021). "Second, PAK1 silencing reduced actin stress fiber formation and in vitro metastatic phenotypes (tumor cell motility and cell adhesion), but not tumorigenic phenotypes (colony formation and cell proliferation) in three OS cell lines." (PMID 31872963, 2020). "Together, these phenotypic analyses suggest that PAK1 is necessary for cytoplasmic p27‐mediated tumor cell migration and adhesion, but not colony formation or proliferation in OS cells." (PMID 31872963, 2020). "The tumor specimens were classified as positive or negative based on a PAK1 staining intensity of ≥0.5 or 0, respectively." (PMID 33261184, 2020). "PAK1-specific inhibitors CEP-1347 and WR-PAK18 selectively inhibited NF2-deficient tumor cells and did not contribute to NF2-positive tumor cells." (PMID 32337368, 2020). "We then investigated whether high expression of PAK1 confers ESCC cell abilities of migration and invasion, which are two of the most important processes in tumor metastasis." (PMID 30971268, 2019). "This stems from the fact that atypical protein kinase Cι binding to Par6 is associated with the epithelial cell transforming sequence 2 (Ect2), a guanine nucleotide exchange factor that activates Rac1 in downstream PAK1, MEK1/2-ERK1/2 signaling, regulating tumor growth in NSCLC." (PMID 31660987, 2019). "Tumor-promoting roles of MAP3K6, PAK1, ALCAM and ITGA6 have been reported, thus their upregulation may also function in the development of NASH-related HCC." (PMID 30367044, 2018). "MiR-98 overexpression was shown to suppress tumor cell proliferation, epithelial-mesenchymal transition (EMT), chemoresistance, and metastasis by targeting p21 (RAC1)-activated kinase 1, SNAIL, and LIN28, while its inhibition leads to tumor metastasis and poor clinical outcome." (PMID 28587210, 2017). "Normal cells, negative control and PAK1-shRNA-expressing cells of DU145 cells were engrafted onto the nude mice (6 mice per group) to monitor tumor growth, respectively." (PMID 28186966, 2017). "PAK1 KO did not affect the numbers of tumours in the colon/rectum, where about 50% of PAK1 WT APC∆14/+ mice had tumours by 10 weeks of age." (PMID 28629331, 2017). "As expected, each primary tumor from all PAK1 WT and PAK1 Y3F mice was positive for myc-tagged PAK1 while GFP cells do not produce tumors." (PMID 27542844, 2016). "Based on these previous findings, we hypothesized that PAK1-mediated stem-like phenotype might induce sunitinib resistance and involve in RCC tumor progression." (PMID 25675297, 2015).
tumor (continued). "Furthermore PAK1 and PAK2 appear to have opposing effects on modulating the phosphorylation of MLC and focal adhesions in tumor cells." (PMID 25379771, 2014). "A step-wise elevation of PAK1 H-score (mean±SEM) in tumor progression: surrounding normal GEJ epithelium (4.000±0.441), atypical hyperplasia (5.200±0.509), stage I tumor (6.400±1.600), stage II tumor (8.000±0.505), and stage III tumor (9.360±0.296)." (PMID 24236193, 2013). "Our analysis using IHC, immunoblot analysis, and data mining indicates that PAK1 is highly differentially over-expressed in GEJ tumor tissues compared with noncancerous tissues." (PMID 24236193, 2013). "Of note is that the remaining 25% (5/20) of tumor samples did not exhibit noticeably upregulated PAK1 versus paired noncancerous controls, of which the majority (3 out of 5) were at the early TNM stage." (PMID 24236193, 2013). "Tightly regulated Dox-mediated knockdown of PAK1 was observed in NSCLC cells and tumor xenografts." (PMID 21653999, 2011). "For this, Western blotting to detect phosphorylated and total levels of the Rac1 effectors p21 activated kinase (PAK-1/2), the RhoA effector Rho kinase (ROCK), and downstream signaling molecules AKT and ERK was done on the pooled tumor extracts from 11 mice per genotype." (PMID 20860838, 2010). "Rac1 and Pak1 proteins were detected in tumor tissues, non-tumor tissues, metastatic lymph nodes, and normal lymph nodes (Figures." (PMID 20426825, 2010). "The level of Pak1 protein was significantly higher in tumor tissues (mean ± S.D. = 2.68 ± 1.26) and metastatic lymph nodes (2.77 ± 1.60) than the level in non-cancerous tissues, which was also set at 1.0, (P < 0.0001, Figure." (PMID 20426825, 2010). "We did not assess Pak1 activity in this study, so its activity in tumor tissues needs to be elucidated in the future." (PMID 20426825, 2010). "We analyzed Rac1 activity and Pak1 protein expression in matched sets of tumor tissue, non-tumor tissue, and metastatic lymph node tissue obtained from the surgical specimens of 108 Japanese patients with UC-UUT." (PMID 20426825, 2010). "Rac1 activity and Pak1 protein levels were higher in tumor tissue and metastatic lymph node tissue than in non-tumor tissue (both P < 0.0001)." (PMID 20426825, 2010). "Our study showed a positive correlation between Rac1 activity and Pak1 expression in tumor tissue, while no such relation was observed in metastatic lymph node tissue." (PMID 20426825, 2010). "Additionally, PAK1 has been shown to cooperate with hypoxia inducible factor 1 subunit alpha (HIF-1α), a transcription factor activated under hypoxic conditions within the tumor microenvironment." (PMID 41459112, 2026). "In this study, PAK1 was depleted in tumour cells rather than endothelial cells." (PMID 40943273, 2025). "Importantly, the absence of PAK1 led to an increase in splenic lymphocytes only in tumor-bearing mice, but not in their tumor-free counterparts, suggesting that the effect is specific for anti-tumor immunity." (PMID 37830586, 2023). "In PAK1 KO mice, the tumour growth was inhibited by PAK1 KO alone without cannabis oil treatment." (PMID 33126623, 2020). "Furthermore, APC (p < 0.0001), ASXL1 (p < 0.0001), DNMT3B (p = 0.001), PARP4 (p = 0.002), MET (p = 0.01), TOP1 (p = 0.01), KDR (p = 0.01), SRC (p = 0.01), PAK1 (p = 0.015), ALK (p = 0.02), and MYC (p = 0.03) alterations were found to be more common in tumor samples from AO mCRC patients." (PMID 33194656, 2020). "Few studies also implied that S2152 phosphorylation of filamin A by other protein kinases, such as PAK1 or RSK, might be involved in the formation of membrane ruffling and lamellipodia extension, the necessary steps for cell migration and tumor cell metastasis." (PMID 25944616, 2015). "We found that PAK1 is highly upregulated in tumor tissues vs. the noncancerous tissues." (PMID 24236193, 2013).